CD14 (CD14 molecule)
Diseases named in the same sentence as CD14 in open-access papers (continued):
Sharing a sentence is not in itself a finding about the gene and the disease.
cancer (272 papers, 2006 to 2026). A tumor composed of atypical neoplastic, often pleomorphic cells that invade other tissues. "Cluster 5 consisted of cancer-associated fibroblasts (CAFs), CD14+ monocytes, CXCL13+ CD4+ follicular helper cells, and GZMA+ CD4+ memory/effector T cells." (PMID 41279139, 2025). "CD14, a co-receptor involved in innate immune responses, has been linked to disease aggressiveness in different cancers 43-45." (PMID 41049426, 2025). "The second type is the population of giant cells that contain cancer proteins and DNA fragments but also express the macrophage-specific protein CD14; these cells are referred to as cancer-associated macrophage-like cells (CAMLs)." (PMID 39456632, 2024). "CD14 was found to be associated with various infectious, metabolic, cardiovascular, and autoimmune diseases and cancers." (PMID 39684692, 2024). "Next, we set out to investigate the cancer-associated factors involved in the differentiation of cDC2s to CD14+ cDC2s." (PMID 38242119, 2024). "CD14 status was associated with cancer-specific survival for the entire cohort and trended towards significance for early-stage patients." (PMID 36139660, 2022). "Echoing what we observed using broad immune phenotypes, IFNγ-producing cytotoxic CD8 (P1_47), as well as CD14 + monocytes (P2_31), were deficient in cancer compared to healthy immunomes." (PMID 36307410, 2022). "Immunohistochemistry to examine the frequency of TAMs and CCL2-expressing cells from paraffin blocks of 137 breast cancer patients found that high frequency of CCL2 positive cancer cells and CD14+ TAMs were significant risk factors for cancer recurrence." (PMID 33297571, 2020). "CD14+HLA-DRlow MDSC have been identified in patients with various cancer types and are associated with a less favorable prognosis." (PMID 31316520, 2019). "We clarified the alterations of mRNA of major immune regulators PD-L1, FOXP3, CD80, CD40, and CD14 in PBMCs of cancer patients and the association of these alternations with disease progression." (PMID 26942414, 2017). "Some studies have indicated that the CD14+ MDSC population is associated with disease progression in cancers." (PMID 26497849, 2015). "There are several polymorphism sites in the CD14 gene, and two well-studied common SNPs in the promoter region of CD14, -260C/T (rs2569190; also reported as CD14 -159) and -561C/T (rs5744455), are investigated extensively to the susceptibility of cancer." (PMID 24978812, 2014). "Two polymorphisms, -260C/T and -651C/T, in the CD14 gene have been implicated in susceptibility to cancer." (PMID 24978812, 2014). "We have conducted the first study to determine the diagnostic potential of the CD14++CD16+ intermediate monocytes as compared to the pro-angiogenic subset of CD14++CD16+TIE2+ TIE2-expressing monocytes (TEMs) in cancer." (PMID 22973451, 2012). "Moreover, within the small intestine, four of five MR-based analytical methods indicate a significant increase in cancer incidence risk associated with CD14+CD16− monocytes." (PMID 38533503, 2024). "Some of the significant cancer hallmark terms are inflammatory response (CD14, CD69, IL10RA), KRAS signaling up (CD37, IL10RA, GPNMB), IL-6/JAK/STAT3 signaling (CD14, CSF2RB), Interferon Gamma Response (CD69, CSF2RB, IL10RA, VCAM1, SLAMF7), TNF-alpha Signaling via NF-kB (CD69)." (PMID 35486660, 2022). "For cancer patients significant difficulties have been described to generate fully activated DCs for clinical use and this deficiency has been linked to the presence of regulatory CD14+HLA-DRlo/neg cells." (PMID 31316520, 2019). "Moreover, more gene-gene and gene-environment interactions should also be considered in future analysis, which should lead to better, comprehensive understanding of the association between the CD14 polymorphisms and cancer risk." (PMID 24978812, 2014).
cancer (continued). "Substantial heterogeneities were observed among studies for the association between the CD14 -260C/T polymorphism and cancer risk under all genetic models (dominant model: I2 = 64%, P = 0.0002; recessive model: I2 = 44%, P = 0.003; CT vs. CC: I2 = 62%, P = 0.0004; TT vs. CC: I2 = 61%, P = 0.0005)." (PMID 24978812, 2014). "In addition, we also explore the association between CD14 -651C/T polymorphism and risk of cancer based on three studies with 832 cases and 1190 controls." (PMID 24978812, 2014). "Elevation of CD14+HLA-DR−/low cells has been described as an indicator of poor prognosis, in terms of patient survival, increased metastasis and poor response to chemotherapy, whereas elevation of HLA-DR in tumors has been associated with favorable outcomes in several cancer types." (PMID 28315927, 2017). "The use of antagonists to block neutrophils and inhibit CD14 expression in cancer cells, which reduces the secretion of neutrophil-recruiting chemokines, effectively mitigated RT-promoted DM in both the MB49 and LLC mouse models." (PMID 41486114, 2026). "Our findings are in line with those results, demonstrating that CD14-high cancer cells promoted greater neutrophil accumulation in the TME than did CD14-low cancer cells." (PMID 41486114, 2026). "CD14 expression has also been found to be upregulated in cancer stem cells to increase their proliferation, migration and metastatic capacity." (PMID 41486114, 2026). "A positive correlation was evident between cancer cell surface PS and CD14 expression induced on the MΦs (r2 = 0.8396, p = 0.0006)." (PMID 40227806, 2025). "These T cells were able to respond to WT levels of MR1 on a wide range of cancer cell lines from many different origins but remained inert to healthy CD14+ monocytes and B cells from multiple individuals." (PMID 39744940, 2025). "In a previous study into DC3 in cancer, we showed that cDC2s from HDs lose their phenotypic plasticity to convert to CD14+DC3s after maturation is induced by activation stimuli." (PMID 40687784, 2025). "In early stages of HCCs, monocytes are capable of eliminating cancer cells, but liver cancer cells induce monocyte transformation into PD-L1/2+ CD14+ cells." (PMID 40136652, 2025). "Within the myeloid compartment, we observed increased levels of classical CD14+ monocytes in patients with mTNBC compared to HDs, reinforcing the notion that cancer induces systemic inflammation." (PMID 39843922, 2025). "On average, the majority of CD45+ cancer cells were also CD14+ (87.62%) and CD16+ (64.74%), with a minor fraction also expressing CD56 (7.80%)." (PMID 40440354, 2025). "Expression of HLA-DR is used to identify CD14+ HLA-DRlo/neg myeloid-derived suppressor cells (MDSC) that negatively correlate with responses to cancer immunotherapy." (PMID 38903497, 2024). "We furthermore show that IL-6 and M-CSF are strong drivers of increased abundance of immune incompetent CD14+ DC3s in the context of cancer and show that pharmacological inhibition of the IL-6R and CSF1R has potential to improve immunotherapy." (PMID 38242119, 2024). "Decreased proportions of CD14.Mn.S100A8.9hi cell subsets were observed in NACT-treated cancer patients compared to healthy controls (log2FC=0,824, FDR=0,1)." (PMID 39315092, 2024). "The polymorphonuclear myeloid-derived suppressor cells (PMN-MDSCs; CD16− CD14− CD11b+ CD33+) play an important role in immune inhibition in the cancer microenvironment, while their role in circulation is still unclear." (PMID 39195280, 2024). "The necessity to study CD14+ DCs in cancer is further highlighted by the impact of defective DCs on immunotherapy efficacy." (PMID 38242119, 2024). "Multiple studies describing CD1c+CD14+ DCs in cancer and healthy state reported similar phenotypes, characterized by co-expression of these monocyte/macrophage markers with cDC2 markers." (PMID 38242119, 2024).
cancer (continued). "Given that pathology is often considered the gold standard for cancer diagnosis, we re-assessed the prognostic value of monocytes (CD14 is a typical marker for monocytes) in the TCGA-OV cohort (cancer tissues)." (PMID 37781709, 2023). "In our present study, IHC analysis showed a significantly high infiltration of CD14+ monocytes in HCMV+ IBC cancer tissues compared to the HCMV- tissues." (PMID 35847899, 2022). "These coculture systems provide an opportunity to directly assess the CD14+-cell-mediated, transcriptional changes acquired by the cancer cell and is a model for exploring the upregulated pathways that potentially impart chemotherapy resistance." (PMID 36139660, 2022). "Vaccination increased the proportion of cytotoxic CD8 T cells as well as CD14 + monocytes which were significantly different between healthy and baseline cancer." (PMID 36307410, 2022). "Significantly decreased percentages of CD19+ B cells and increased percentages of CD14+ monocytes were found in cancer patients’ PBMCs." (PMID 35203349, 2022). "To further understand the mechanism contributing to decreased monocyte-induced NK cell activation, we next determined the levels of CD16 surface expression on CD14+ monocytes of healthy individuals and those of the cancer patients using flow cytometry." (PMID 35203349, 2022). "Statistical analysis of IHC imaging data showed a significant (P= 0.04) infiltration of CD14+ monocytes in HCMV+ IBC cancer tissues compared to the HCMV- tissues." (PMID 35847899, 2022). "Using an in vitro model system, we found that CD14+ cells reduced chemotherapy-induced cancer cell death." (PMID 36139660, 2022). "Among them, five targets (APOH, CD14, ICAM1, LRG1 and SERPINC1) were reported to be associated with other cancers or prognostic significance." (PMID 34199928, 2021). "CD14+cDC2 cells identified in the peripheral blood, ascites and within tumors of cancer patients represent another promising tolerogenic DC subset." (PMID 34445143, 2021). "It was confirmed that numerous CD14+ cells existed in the peritoneal cavity along with GFP-positive cancer cells." (PMID 33509150, 2021). "Although cancer cells differ from primary macrophages in inter alia expression of LPS receptor CD14, they responded similarly to LPS also in terms of PARP1 contribution to the induction of endotoxin tolerance." (PMID 33671709, 2021). "Because both analyses showed that OLFML2B was positively correlated with macrophage content, we input cancer-related macrophage markers into the web tool “CellMarker” and obtained experimentally verified markers: CD14, CD68, CD163, CSF1R, ITGAM, and MRC1." (PMID 34868901, 2021). "Consistent with preclinical studies, CD45bright/CD14+ monocytes expressing VEGFR2 become dominant in circulating blood from patients with cancer compared with healthy donors." (PMID 34673569, 2021). "We encapsulated pancreatic cancer-associated antigen WT1 short peptide into the liposomes, and incubated them with CD14+ isolated monocytes." (PMID 34394090, 2021). "Flow cytometry analysis of CD14+16-, CD14+16+, and CD14low16+ in healthy female and cancer patients’ group." (PMID 35237501, 2021). "CD14+ HLA-DRNeg/Low peripheral monocytes have immunosuppressive functions in patients with different types of cancer and increase was connected with poor prognosis in cancer." (PMID 32899681, 2020). "However, it is unclear whether cancer progression is associated with CD14+ cells." (PMID 32824016, 2020). "Cancer stem-like cells can generate M2-like immunoregulatory myeloid cells from CD14+ monocytes by producing a variety of proinflammatory cytokines, including M-CSF." (PMID 32487125, 2020). "(d) Kaplan–Meier curves for cancer specific survival in patients with PD–L1+PD–L2+ CD14+ cells (n = 30; red line) and patients with other types of CD14+ cells (n = 57; blue line)." (PMID 32587357, 2020).
cancer (continued). "Those patients expressing high levels of PD–L1 and PD–L2 on their CD14+ cells were found to show shorter overall survival, with most deaths being cancer-related." (PMID 32587357, 2020). "We compared CD14+ cell properties before and after cancer progression in the same HCC patients and examined their role in antitumor immunity." (PMID 32824016, 2020). "In this study, PD-Ls were found to be expressed in CD14+ cells in HCC patients over time as the cancer progressed." (PMID 32824016, 2020). "Some other studies have reported reduced HLA-DR expression on blood monocytes in human cancer, but mainly on CD14 positive monocytes." (PMID 32899681, 2020). "Afterwards, we explored alterations in SIRPα levels in the phagocytic macrophages, those engulfing CFSE+ cancer cells (CD14+CFSE+)." (PMID 32231135, 2020). "On the other hand, many cancer patients have been observed with normal levels of CD14+HLA-DRlo/neg monocytes." (PMID 31191529, 2019). "One study that has used CD14+ in conjunction with CD11b and the vitronectin receptor or αvβ3 showed that peripheral blood of osteolytic cancers contained more VNR+ monocytes, which correlated to higher osteoclast formation." (PMID 30941138, 2019). "While CD14+ MDSCs represented approx. 35% of total MDSCs in healthy controls, in cancer patients before treatment approx. 70% of total MDSCs were CD14+." (PMID 31500214, 2019). "We demonstrated that CD14+ARG1+ cells were significantly increased in cancer patients as compared to the HDs." (PMID 31533831, 2019). "The extent of phagocytosis was evaluated using flow cytometry by determining the percentage of cells staining double positive for PKH67 and anti-CD14-APC or anti-CD11b-APC over the total number of PKH67+ cancer cells." (PMID 30984171, 2019). "Dendritic cells (DCs), which can be used as anti-cancer vaccines, are generally obtained in vitro from isolated CD14+ monocytes (MoDCs)." (PMID 29434528, 2018). "Elevation of CD163, PD-L1 and IL-10 expression on CD14+ monocytes from PBMCs of cancer patients was observed as compared to those from healthy donors." (PMID 30563569, 2018). "Recently, we identified a novel population of immunosuppressive myeloid cells that co-expresses BDCA1 and CD14 in blood and tumors of cancer patients." (PMID 30235890, 2018). "Peripheral blood CD14+ monocytes from healthy donors treated with TRAPs from cancer patients exhibited a significant increase in CD163 and PD-L1 expression and a decrease in HLA-DR expression." (PMID 30563569, 2018). "BDCA1+CD14+ cells are also present in blood of healthy donors, but at much lower levels than in cancer patients." (PMID 30235890, 2018). "We have previously demonstrated that the loss of HLA-DR is associated with the immunosuppressive activity of monocytes (CD14+HLA-DRlo/neg) in cancer patients." (PMID 28742871, 2017). "As result, many authors have relied only on CD14 and HLA-DR staining to identify monocytic MDSCs in cancer patients, either alone or as a surrogate after first identifying a population of MDSCs that are CD11b+/CD14+/CD15-/HLA-DR-." (PMID 28666020, 2017). "We consider that it is possible that the technology based on the CD14-ML will be able to change the current situation of anti-cancer vaccination therapy." (PMID 27050553, 2016). "Collectively, the generation of CD14-ML-DC derived from monocytes of cancer patients was feasible, and the cancer patient-derived CD14-ML-DC were sufficiently potent to induce antigen-specific T cell responses." (PMID 27050553, 2016). "The capacity of CD14-ML-DC to induce vigorous T cell proliferation and cancer antigen-specific T cells demonstrated in this study indicates a potential value in vaccination therapy." (PMID 27050553, 2016). "As a result, we successfully established CD14-ML from monocytes obtained from the 2 cancer patients (cancer patient 1 and 2), and the CD14-ML were able to differentiate into CD14-ML-DC after stimulation with IL-4." (PMID 27050553, 2016).
cancer (continued). "Laricitrin treatment stimulated DC differentiation and maturation in the condition media of cancer cells, a finding supported by monocyte marker CD14's disappearance and DC marker CD1a's upregulation." (PMID 27833081, 2016). "In vitro stimulation of peripheral blood T cells with CD14-ML-DC that were loaded with cancer antigen-derived peptides led to the establishment of CD4+ and CD8+ T cell lines that recognized the peptides." (PMID 27050553, 2016). "Although it cannot be definitively concluded that HER2 was transferred from the cancer cells to the CD14+ and CD56+ cells by trogocytosis, the observation is significant because HER2 expression is not usually observed on CD14+ and CD56+ cells in normal PBMCs." (PMID 25655677, 2015). "When CD11b+CD14+ cells were co-cultured with cancer cells, both the invasion and the proliferation of cancer cells were robustly promoted and these promotions were almost completely inhibited by pretreatment with anti-IL-6R antibody (tocilizumab)." (PMID 25658637, 2015). "It has been found that the frequency of CD14+HLA-DRlow/− cells is increased in the peripheral blood from cancer patients." (PMID 26230952, 2015). "CD14+ HLA-DRlo/neg monocytes suppress autologous T cell proliferation and are defective in their ability to differentiate into mature dendritic cells in cancer patients." (PMID 26286851, 2015). "Cancer cells and monocytes were of a similar size but monocytes were CD14+ (cancer cells indicated by red circle and monocytes indicated by yellow circle)." (PMID 25655677, 2015). "In monocytes, an increase in CXCR4 expression has been shown in CD14+CD16− cells cultured with cancer cells, alongside increases in the expression of CCR2, CXCR1 and CXCR2." (PMID 25251539, 2014). "In the current study, cancer cell-conditioned medium and IL-10 induced higher expression levels of CD14, CD16 and CD163 with normal DC markers, including CD11c and CD209." (PMID 25013476, 2014). "InfDCs (CD14+ CD16− BDCA1+) in cancer ascites were separated from macrophages (CD14+ CD16c+ BDCA1−) and then further characterized for the expression of additional markers (CD11c+ CD11b+ HLA-DR+ BDCA1+ CD206+)." (PMID 24432020, 2014). "The finding that CD14+HLA-DRlo/neg monocytes are detectable systemically in patients with a variety of malignancies and that they are functionally immune suppressive raises important questions regarding their influence in ex vivo DC vaccine preparations." (PMID 24772111, 2014). "The results seem to contradict the observations of functional studies of CD14, which had suggested that CD14 played an important role in the development of cancer." (PMID 24978812, 2014). "Variants in several innate immunity genes have been identified as biologically plausible candidates for effects on cancer, such as CD14." (PMID 24978812, 2014). "Each of these classes of DCs has been demonstrated to play a key role in immune surveillance and response but for the purpose of DC-based vaccines for immunotherapy in cancer, the focus has been on CD14+ monocyte-derived DCs." (PMID 24772111, 2014). "The CD14+ monocytes isolated from the healthy donors were treated with PAO or CD45i prior to the addition of 20% cancer cell-conditioned medium." (PMID 25013476, 2014). "Our studies identified a deficiency in the ability to generate mature dendritic cell using CD14+ cells from cancer patients that corresponded with an increased population of monocytes with altered surface marker expression (CD14+HLA-DRlo/neg)." (PMID 24772111, 2014). "Over a course of three separate dendritic cell vaccine studies to treat cancer, we tested two different methods for preparing dendritic cells from peripheral blood mononuclear cells: adherence and antibody-selected CD14+ cells." (PMID 25475068, 2014). "The inverse relationship between these two cells types has not been explicitly described before and these results suggest that the CD4/CD14+HLA-DRlo/neg monocyte ratio is an important biomarker for cancer prognosis." (PMID 25512872, 2013).